RN7SL416P (RNA, 7SL, cytoplasmic 416, pseudogene)
Gene: Miscellaneous RNA gene on chromosome 7 (100,530,362 to 100,530,659, reverse strand). Ensembl gene ENSG00000242101.
Homologues: Orthologues: chimpanzee Metazoa_SRP (99% identical), macaque Metazoa_SRP (94% identical). Paralogues in human: RN7SL1 (84% identical), RN7SL2 (83% identical), RN7SL3 (82% identical), RN7SL220P (82% identical), RN7SL126P (82% identical), RN7SL709P (81% identical), RN7SL597P (81% identical), RN7SL113P (80% identical), RN7SL507P (80% identical), RN7SL786P (80% identical), RN7SL333P (80% identical), RN7SL566P (80% identical), and 702 more.